SNORD115-40 (small nucleolar RNA, C/D box 115-40)
Synonyms: HBII-52-40
Gene: Small nucleolar RNA gene on chromosome 15 (25,243,614 to 25,243,695, forward strand). Ensembl gene ENSG00000272460.
Gene Ontology:
Biological process: RNA processing
Cellular component: nucleolus
Homologues: Paralogues in human: SNORD115-12 (99% identical), SNORD115-13 (99% identical), SNORD115-21 (99% identical), SNORD115-9 (99% identical), SNORD115-10 (98% identical), SNORD115-11 (98% identical), SNORD115-16 (98% identical), SNORD115-20 (98% identical), SNORD115-29 (98% identical), SNORD115-36 (98% identical), SNORD115-42 (98% identical), SNORD115-43 (98% identical), and 37 more.